IL1B (interleukin 1 beta)
Diseases named in the same sentence as IL1B in open-access papers (continued):
Sharing a sentence is not in itself a finding about the gene and the disease.
Peri-Implantitis (continued). "Plenty of studies showed that the level of IL-1β in PICF is increased in patients with peri-implantitis condition." (PMID 33376734, 2020). "At the oral level, several studies have demonstrated the presence of high levels of IL-1α and IL-1β in crevicular fluid and in saliva of patients with active peri-implantitis lesions." (PMID 30386510, 2018). "The IL-1β/ IL-10 ratio was found to be 9.9 ± 11.9 for the healthy group and 37.2 ± 44.4 for the peri-implantitis group (p = 0.006)." (PMID 25888355, 2015). "Furthermore, the application of hyaluronic acid in patients with peri-implantitis led to a significant reduction in IL-1β levels in the gingival crevicular fluid compared with the pre-application period." (PMID 40360766, 2026). "Most studies focused on peri-implantitis and evaluated serological markers such as C-reactive protein and cytokines (IL-6, IL-1β, IL-17, tumour necrosis factor-α), along with haematological parameters including neutrophils, haemoglobin, platelets, and lymphocytes." (PMID 41301163, 2025). "Statistical analysis (t-tests and correlations, p < 0.05) revealed significantly elevated levels of IL-1β, MMP-8 and TNF-α in peri-implantitis patients, with IL-1β and MMP-8 strongly correlating with probing depth and TNF-α moderately correlating with bone loss." (PMID 41907937, 2025). "Additionally, IL-1β levels were significantly higher in the peri-implantitis group than those in the healthy group." (PMID 38874661, 2024). "The median values for IL-1β in each group were as follows: 0.03 (0.01–0.08) μg/site in the healthy group, 0.15 (0.09–0.30) μg/site in the mucositis group, and 0.08 (0.02–0.51) μg/site in the peri-implantitis group." (PMID 38874661, 2024). "For this reason, as with IL-1β, it can serve a prognostic role in peri-implantitis progress." (PMID 37232785, 2023). "Additionally, contrary to IL-6, IL-1β levels are lower in peri-implantitis than in peri-implant mucositis, highlighting other possible factors contributing to bone resorptions." (PMID 37232785, 2023). "This makes IL-1β particularly interesting in the case of diagnostics, as it may serve as a predictor of the severity of peri-implantitis." (PMID 37232785, 2023). "Furthermore, there is some evidence suggesting that IL-1β is the main proinflammatory biomarker in active peri-implantitis regions; thus, it can be used as an early indicator of peri-implant disease." (PMID 35637753, 2022). "Finally, the potential target genes, namely, IL-6, TLR4, FN1, IL-1β, CXCL8, MMP-9, and SPP1, were found to be associated with peri-implantitis, and our results were consistent with those of previous studies." (PMID 34931168, 2021). "The most used biomarkers to assist the early diagnosis of peri-implantitis are IL-1β and TNF-α." (PMID 33111201, 2020). "The level of IL-1β around peri-implantitis lesion has a positive influence on the quantity of gingival inflammation, demonstrating that it is a reliable indicator to diagnose peri-implant mucositis in an early stage before it advances to peri-implantitis." (PMID 33376734, 2020). "Moreover, IL-1β is known as a decisive factor for differentiating healthy implants and peri-implantitis from each other." (PMID 33376734, 2020). "To determine whether the down-regulation of miR-128 in peri-implantitis is related to IL-1β, we examined the expression of miR-128 under osteoinductive conditions with or without stimulation of IL-1β for 1, 3, 7, and 14 days." (PMID 31985779, 2020). "IL-1A-C889T, IL-1B+C3953T and IL-1RN+T2018C were identified by polymerase chain reaction (PCR) amplification in order to establish a relation between these variables and the presence of peri-implantitis." (PMID 26449434, 2015).
Peri-Implantitis (continued). "Nevertheless, consistent associations were observed for certain polymorphisms—particularly CD14 rs2569190, IL-1β +3954 C/T, and TNF-α −308 G/A—across independent populations, supporting a moderate level of confidence in these findings as potential biomarkers for peri-implantitis susceptibility." (PMID 41373620, 2025). "Therefore, IL-1β levels may be elevated in peri-implantitis, where tissue destruction around the implant allows for easier passage of the protein through vessel walls." (PMID 38874661, 2024). "Furthermore, the findings suggest that IL-17, sclerostin and IL-1β may serve as promising biomarkers for assessing efficacy of peri-implantitis treatment." (PMID 39080143, 2024). "However, we did observe a risk association between the presence of the C/C genotype of the SNP IL-1β (− 511) and peri-implantitis (T/C vs T/T: I2 = 0%, p = 0.921; OR: 0.902; IC 95% 0.510–1.595 and C/C vs T/T: I2 = 0%, p = 0.555; OR: 2.255; IC 95%: 1.040–4.889)." (PMID 35061134, 2022). "Osteopontin (OPN) may play a decisive role in the production of IL-1β and apoptosis in peri-implantitis, as confirmed by the analysis of the patient's PICF and cell-culture examination, decreasing inflammation through proinflammatory cytokines' downregulation in peri-implantitis." (PMID 33376734, 2020). "Therefore, it is of interest to evaluate the diagnostic efficacy of salivary biomarkers-interleukin-1β (IL-1β), matrix metalloproteinase-8 (MMP-8) and tumour necrosis factor-alpha (TNF-α)-by comparing their concentrations in patients with healthy peri-implant tissues and those with peri-implantitis." (PMID 41907937, 2025). "The aim was to evaluate the association between single-nucleotide polymorphisms (SNPs) in genes involved in inflammation and bone metabolism (BMP-4, BRINP3, CD14, FGF-3, FGF-10, GBP-1, IL-1α, IL-1β, IL-10, LTF, OPG, and RANKL) and peri-implantitis." (PMID 41373620, 2025). "Several studies have reported higher levels of IL-1β and tumor necrosis factor-alpha (TNF-α) in the peri-implant crevicular fluid (PICF) of implants with peri-implantitis than in healthy implants." (PMID 38203822, 2024). "For IL-1β and IL-Ra levels, only one study was included and observed higher levels of IL-1β and lower levels of IL-Ra in PICF of individuals with peri-implantitis in comparison to healthy individuals." (PMID 37355561, 2023). "IL-1β and sIL-6R levels in the PICF were significantly higher in the peri-implantitis group than in the healthy group." (PMID 36834667, 2023). "Furthermore, the fact that the other studies that also analyzed this SNP did not observe such link, with more precise diagnostic criteria of PI, make us believe that the C/C genotype of IL-1β (− 511) would truly be associated to alveolar bone loss and not actual peri-implantitis." (PMID 35061134, 2022). "In this study, pro-inflammatory cytokines of IL-1β, IL-6, IL-17A, and TNF-α were significantly higher in peri-implantitis than those in healthy implants, and this result is consistent with another study." (PMID 36233685, 2022). "This eventually activates the transcription factor NF-κB, which regulates a large range of cytokines, including IL-1β, TNF-α, and RANKL/OPG; many of them have been shown to play a pathologic role in peri-implantitis." (PMID 34401982, 2021). "The intersecting genes, including IL6, TLR4, FN1, IL1β, CXCL8, MMP9, and SPP1, were revealed as potential genetic biomarkers and target genes of peri-implantitis." (PMID 34931168, 2021). "LPS from P. gingivalis, another peri-implantitis-related pathogen, increases the mRNA levels of NLRP3, ASC, and caspase-1 in BMSCs, thereby increasing IL-1β production." (PMID 34177950, 2021). "This is supported by the findings that significantly higher levels of IL-1β and TNFα in the peri-implant crevicular fluid (PICF) are observed in patients with peri-implantitis than in healthy controls." (PMID 34610045, 2021).
Peri-Implantitis (continued). "In the present study, our results showed that the proinflammatory cytokines IL-6, IL-1β, and CXCL8 were upregulated in peri-implantitis." (PMID 34931168, 2021). "Hence, we could hypothesize that the inhibitory effect of IL-1β on miR-128 expression might be one of the reasons for repressed osteoblast differentiation in peri-implantitis and that miR-128 might play a positive role during osteogenic differentiation by regulating DKK2 expression." (PMID 31985779, 2020). "The expression levels of other pro-inflammatory factors, such as IL-1β, Il-6, IL-8, and TNF-α, were also higher in the GCF from peri-implantitis sites than in the GCF from healthy sites." (PMID 32760399, 2020). "According to the results, IL-1β, IL-6, and TNF-α, levels were significantly higher in mucositis and peri-implantitis than in healthy implants." (PMID 33291232, 2020). "As expected, the presence of inflammatory cytokines and chemokines, particularly IL1B, IL6, its signal transducer IL6ST, and CXCL2, was clearly observed at the mRNA level in the peri-implantitis affected samples." (PMID 31242601, 2019). "This preclinical study therefore advocates that neutralizing antibodies be further tested against IL1β, IL6, or TNFα in clinical settings for managing the aseptic loosening of orthopedic prostheses and oral peri-implantitis." (PMID 30619321, 2018). "Reducing IL-1β and TNF-α is crucial for enhancing the longevity of dental implants because these cytokines are key mediators in the inflammatory process that can lead to peri-implantitis." (PMID 39590543, 2024). "The level of chemical mediators, such as interleukin (IL)-1β, tumor necrosis factor (TNF)-α, and calprotectin, in peri-implant crevicular fluid (PICF) correlates with the progression of peri-implantitis and its usefulness as a biomarker of peri-implant disease is becoming clear." (PMID 36834667, 2023). "Moreover, IL-1β and TNF-α were significantly higher in CVD patients, which were significant markers for peri-implantitis." (PMID 37745126, 2023). "Levels of IL-1β and MMP-8 were significantly elevated in implants with peri-implantitis." (PMID 36997949, 2023). "In the same individual, peri-implantitis sites harbored more abundance of Treponema, Peptostreptococcaceae XIG-1, Porphyromonas, and Lachnospiraceae G-8, as well as cytokines of IL-6, IL-17A, G-CSF, RANTES, and IL-1β, than healthy implants sites." (PMID 36233685, 2022). "We found that IL-6, TLR4, FN1, IL-1β, CXCL8, MMP-9, and SPP1 might be used as potential biomarkers for the diagnosis of peri-implantitis." (PMID 34931168, 2021). "This study provides supportive evidence that IL6, TLR4, FN1, IL1β, CXCL8, MMP9, and SPP1 might be used as potential target biomarkers for peri-implantitis which may provide further therapeutic potentials for peri-implantitis." (PMID 34931168, 2021). "Additionally, levels of IL1β were significantly higher in whole salivary samples and PISF samples collected from patients with peri-implantitis, compared with healthy controls." (PMID 33081038, 2020). "Both IL-1β and TNF-α are important mediators of the pathogenesis of peri-implantitis." (PMID 28864780, 2017). "Peri implant mucositis shows significantly increased levels of IL-1β, aMMP8, procalcitonin, bone turnover marker RANKL and salivary alpha amylase while IL-1β, VEGF, MMP8, Procalcitonin, RANKL, Osteoprotegerin (OPG) are all significantly elevated in peri implantitis." (PMID 41584075, 2025). "However, IL-1β levels between peri-implantitis and peri-implant mucositis were not statistically different." (PMID 39195095, 2024). "A meta-analyses that combined seven researches determined that interleukin-1beta (IL-1β) and tumor necrosis factor‐alpha (TNF-α), can be used as supplementary criteria for diagnosis of peri-implant infection, although cannot be used to distinguish peri-implant mucositis from peri-implantitis." (PMID 36997949, 2023).
Peri-Implantitis (continued). "In agreement, lower proinflammatory cytokines (IL-1β and IL-6) and RANKL/OPG ratio were observed in peri-implant mucositis individuals in comparison to peri-implantitis individuals; this could be due to the lower peri-implant mucositis severity compared to peri-implantitis." (PMID 37355561, 2023). "Another two systemic reviews presented that pro-inflammatory cytokines in PICF, such as IL-1β, TNF, and IL-6, were significantly elevated in peri-implantitis and could be used as adjunct tools to clinical parameters to differentiate healthy implants from peri-implantitis." (PMID 36233685, 2022). "During the treatment of peri-implant mucositis and peri-implantitis there were minimal effects of non-surgical treatment alone on the investigated inflammatory biomarkers (IL-4, IL-10, and IL-12, TNF-a, RANKL, OPG IL-1β, IL-6, TNF-α, MCP-1/CCL2, MIP-1α/CCL3, IFN-γ, MMP-8, sRANKL, OPG and G-CSF)." (PMID 36360962, 2022). "Our Endocan findings contrast markedly with traditional inflammatory mediators, where Unlike IL-1β and TNF-α which typically elevate in both mucositis and peri-implantitis (Dursun and Tözüm, 2016), Endocan demonstrated specificity for peri-implantitis only." (PMID 40739222, 2025). "In peri-implantitis, LPS + Ti strongly activates NLRP3, but without AIM2 activation, IL-1β and pyroptosis remain lower than in WT cells." (PMID 40490723, 2025). "IL-1β (p < 0.01), IL-6 (p < 0.01), IL-10 (p < 0.05) and TNF-α (p < 0.01) are significantly higher at the sites with peri-implantitis compared to healthy peri-implant tissue, while IL-8 did not increase significantly." (PMID 25888355, 2015). "In this study, it was found that IL-1β (p < 0.01), IL-6 (p < 0.01), IL-10 (p < 0.05) and TNF-α (p < 0.01) were significantly increased at the sites with peri-implantitis, while IL-8 was not." (PMID 25888355, 2015). "Thus, we show that salivary IL-1β, MMP-8 and TNF-α show strong potential as reliable, non-invasive biomarkers for early detection and monitoring of peri-implantitis." (PMID 41907937, 2025). "The results showed that the levels of IL-1β, IL-6, IL-10, and RANKL/OPG are not balanced in peri-implant disease, suggesting that these mediators are involved in the host osteo-immunoinflammatory response related to peri-implantitis." (PMID 37355561, 2023). "This study evaluated the presence of cytokines (IL-1β, IL-2, IL-4, IL-6, MCP-1, MIP-1α, MIP-1β, and TNF-α) and human herpesvirus (HSV1, HSV2, EBV, CMV, VZV, HHV6, HHV7, and HHV8) in saliva samples taken from subjects with and without peri-implantitis." (PMID 30158834, 2018).
chronic kidney disease (88 papers, 2012 to 2026). Impairment of the renal function secondary to chronic kidney damage persisting for three or more months. "Chrysin ameliorates adenine-induced chronic kidney disease, which causes inflammation by increasing the plasma concentration of IL-1β and IL-6." (PMID 36552226, 2022). "EVs extracted from umbilical cord-derived MSCs have attenuated TNF-α, IL-6, and IL-1β levels, and increased IL-10 level in a model of chronic renal failure following I/R injury." (PMID 40535418, 2025). "In chronic kidney disease (CKD) models, elevated IL1B levels are associated with glomerulosclerosis and proteinuria progression." (PMID 40661082, 2025). "Chronic renal failure patients and animal models of acute kidney injury (AKI) caused by nephrotoxic drugs have shown increased levels of IL-6, IL-1β, and TNF-α." (PMID 39468702, 2024). "The injection of IL-1β antibodies to neutralize circulating IL-1β prevents cardiac structural remodeling and reduces the incidence of AF in a mouse model of chronic kidney disease." (PMID 38391924, 2024). "Studies have tied various pro-inflammatory molecules (e.g. tumor necrosis factor-alpha (TNF-α), interleukins 1β and 6 (IL-1β, IL-6) etc.)to the onset of chronic kidney disease (CKD)." (PMID 39469576, 2024). "It should also be noted here that the available literature indicates that the level of IL-1β is decisively higher in patients with chronic renal disease than in the control group." (PMID 37629400, 2023). "Co-administration of chrysin with adenine showed a significant decrease in the levels of TNF-α, IL-1β, sclerostin, and endothelin-1, indicating the ability of chrysin in attenuating adenine-induced chronic kidney disease through an anti-inflammatory mechanism." (PMID 36552226, 2022). "According to previous studies, enhanced IL-1β expression is disturbed processes of contextual fear conditioning, and this response is affected by uremic toxin due to chronic kidney disease." (PMID 35884712, 2022). "In a chronic renal insufficiency cohort study, inflammation markers (IL-1β, IL-1 receptor antagonist, IL-6, TNF-α, hs-CRP, and fibrinogen) were associated with decreased kidney function." (PMID 35628912, 2022). "Shen Shuai II Recipe significantly reduced RIF and downregulated the expression of HIF-1α, c-Myc, and IL-1β proteins in 5/6 (A/I) rats with chronic renal failure." (PMID 34211565, 2021). "Cytokines such as IL-6, TNF-α and IL-1β trigger inflammatory cascades which may play a role in the pathogenesis of chronic kidney disease (CKD)-associated cachexia." (PMID 34302016, 2021). "IL-1β, IL-6, and TNFα are important cytokines that serve as essential mediators of the immune response and inflammatory reactions in patients with chronic renal failure." (PMID 34463195, 2021). "It has been reported in the pathogenesis of chronic kidney disease, and excessive ROS has been reported to activate mediator signalling molecules which trigger the production of inflammatory cytokines such as IL-1β or TNF-α." (PMID 32975098, 2020). "Production of IL-1β from monocytes isolated from patients with chronic kidney disease (CKD) or with RA will also be studied for comparison." (PMID 30761138, 2019). "In this study, we show for the first time that a novel formulation of curcumin with improved bioavailability improves cardiac function by suppressing NLRP3 inflammasome activation and mature IL-1β release in rat model of chronic kidney disease." (PMID 28000751, 2016). "Both IL-1β and IL-6 are important cytokines which are essential mediators of immune response and inflammatory reactions in patients with chronic renal failure." (PMID 23990847, 2013). "In chronic kidney disease, mitochondrial dysfunction, oxidative stress, immune dysfunction, and chronic low-grade inflammation are common, as reflected by elevated levels of circulating inflammatory markers, such as IL-1β, IL-6, and C-reactive protein." (PMID 40725180, 2025).